IL24 (interleukin 24)
Diseases named in the same sentence as IL24 in open-access papers (continued):
Sharing a sentence is not in itself a finding about the gene and the disease.
tumor (continued). "Secreted IL-24 protein also generates a strong expression of endogenous IL-24, and subsequent induction of tumor-specific killing by ER stress activation and reactive oxygen species production." (PMID 30424508, 2018). "The tumor suppressor activities of IL-24 include the inhibition of angiogenesis, invasion, and metastasis, sensitization to chemotherapy, and the induction of cancer-specific apoptosis." (PMID 30424508, 2018). "This suggests that the augmented efficacy of the CRAds depended primarily on the anti-tumor activities of IL-24." (PMID 30477117, 2018). "Interleukin 24 (IL-24) is a tumor-suppressing protein, which inhibits angiogenesis and induces cancer cell-specific apoptosis." (PMID 30424508, 2018). "Understanding the complexities of IL-24 induction of apoptosis in cancer cells significantly broadens its potential as an anti-tumor therapeutic and reveal new combinatorial strategies for targeted cancer therapies." (PMID 30424508, 2018). "In contrast, the effects of expressing IL-24 were significant and most prominent anti-tumor effects, including complete tumor regression, were achieved with the virus carrying both miR-34a and IL-24." (PMID 30477117, 2018). "In contrast, mice injected with both B16-F10 cells and IL24-iMSCs developed detectable tumors on day 9 with an average tumor volume of 643.64 mm3 on day 19, thereby demonstrating the inhibitory effects of IL24-iMSCs on tumor development." (PMID 28388559, 2017). "Immunofluorescence and histochemical analysis showed larger necrotic areas and cell nuclear aggregation in tumors with IL24-iMSCs than control iMSCs, indicating that IL24-iMSCs inhibited tumor growth by inducing apoptosis." (PMID 28388559, 2017). "More importantly, IL24-iMSCs suppressed tumor growth more effectively than control iMSCs demonstrating the anti-tumor effects of transgenic IL24." (PMID 28388559, 2017). "IL24 was also shown to function as a tumor suppressor in hematological malignancies and to cause apoptosis by a secretory pathway in NSCLC, while IL24 overexpression suppressed migration and invasion in LAD." (PMID 28109288, 2017). "Meanwhile, the weight of tumor in the control mice injected with B16-F10 cells was 6.3 fold larger than mice injected with both B16-F10 cells and IL24-iMSCs and 1.3 fold larger than mice injected with both B16-F10 cells and iMSCs." (PMID 28388559, 2017). "The volume of tumor in the control mice injected with B16-F10 cells was 3.6 fold larger than mice injected with both B16-F10 cells and IL24-iMSCs and 1.4 fold larger than mice injected with both B16-F10 cells and iMSCs." (PMID 28388559, 2017). "The gene for IL‐24 has been reported as a tumor suppressor and IL‐24 plays prominent roles in various cancers such as by inhibiting tumor growth, invasion and metastasis and promoting cell death." (PMID 28781949, 2017). "In situ pathological examination of H&E stained tumor tissues from the mice injected with B16-F10 cells and either IL24-iMSCs or iMSCs showed necrotic areas and aggregation of cell nuclei in the tumor area." (PMID 28388559, 2017). "Synergistic tumor cell inhibition was observed for 5-Fu in combination with Ad-hTERTp-IL24, as well as AdTrack in vitro and in vivo." (PMID 27322080, 2016). "IL-24 is a promising anticancer agent for the treatment of a wide variety of tumor cell types and has shown significant benefit in patients." (PMID 27203744, 2016). "IL-24 is a novel tumor suppressor gene that has demonstrated anti-tumor effects in a broad spectrum of human cancers." (PMID 27602961, 2016). "We also thought to assess the utility of CRAd arming with ING4 gene, which was previously shown to provide growth suppression of several tumor types, when being expressed alone or together with IL-24 gene using replication-incompetent Ad vectors." (PMID 27349517, 2016). "Further, the combination of IL-24 and HMGA1 silencing more strongly inhibited AKT signaling and the associated tumor cell migration and invasion." (PMID 27602961, 2016).
tumor (continued). "The tumor suppressor activities of IL-24 include inhibition of angiogenesis, sensitization to chemotherapy, and induction of cancer-specific apoptosis." (PMID 27271601, 2016). "In vitro and in vivo studies in a broad spectrum of human cancer cells demonstrated that exogenous IL-24 expression has anti-tumor, anti-angiogenic, and anti-metastatic properties and suppresses various signaling pathways, without harming normal cells." (PMID 27602961, 2016). "Interleukin (IL)-24, a novel tumor suppressor/cytokine exhibits antitumor activity against a broad-spectrum of human cancer cells." (PMID 27602961, 2016). "IL-24 displays a broad range of activities including antibacterial responses, tissue remodeling, wound healing, and anti-tumor effects." (PMID 27271601, 2016). "Several tumor suppressor genes, including E-cadherin, IL-24, IL-32 and p21 have been reported to be activated by miRNAs through targeting specific sites in their promoters." (PMID 27429046, 2016). "In this study, the therapeutic adenoviruses were delivered to tumor sites and amplified by HUMSCs sequentially infected by Ad-hTERTp-IL24 and LentiR.E1A." (PMID 27322080, 2016). "The tumor cell killing ability was significantly increased when HepG2 were treated with Ad-hTERTp-IL24 in combination with 5-Fu, compared with Ad-hTERTp-IL24 or 5-Fu treatment alone." (PMID 27322080, 2016). "Phase I trials of intratumoral injections of Ad.IL-24 (INGN241) have demonstrated that Ad.IL-24 is well tolerated and induces apoptosis in tumor cells with s significant clinical activity." (PMID 27271601, 2016). "Immunohistochemistry showed marked IL-24 expression (red) around the tumor cells (green) in the group treated with MSC.LentiR.E1A+Ad-hTERTp-IL24." (PMID 27322080, 2016). "MSC.LentiR.E1A+ Ad-hTERTp-IL24 treatment exhibited significant anti-tumor effects on the transplanted hepatocarcinoma, which were mediated by Ad-hTERTp-IL24." (PMID 27322080, 2016). "The results showed that Ad-hTERTp-IL24 inhibited the growth of HepG2 cells, but not of MRC-5 cells, suggesting that the hTETR promoter, as well as IL-24, play a positive role only in tumor cells." (PMID 27322080, 2016). "After exogenous addition of IL-24, apoptosis is induced in tumor cells independently of the JAK/STAT pathway." (PMID 27271601, 2016). "At supra-physiological levels, MDA-7/IL-24 plays a prominent role in inhibiting tumor growth, invasion, metastasis and angiogenesis resulting in selective cancer cell death without affecting normal cells." (PMID 27349517, 2016). "TAT-IL-24-KDEL has been shown to efficiently transfer into tumor cells and locate on ER, consequently inducing cell apoptosis to a much greater extent than IL-24 and TAT-IL-24." (PMID 27203744, 2016). "Similar results were seen in a dose-escalation study of Ad.IL-24 where tumor cells underwent apoptosis in patients after successful gene transfer of IL-24." (PMID 27271601, 2016). "Recently, we reported that IL-24 effectively suppressed AKT/mTOR signaling and its associated tumor cell migration." (PMID 27602961, 2016). "SDF-1-induced chemotactic activity of tumor cells was markedly reduced in the presence of AMD3100 or IL-24 alone when compared to control cells (P<0.05)." (PMID 25775124, 2015). "Pre-clinical studies showed that exogenous expression of human IL-24 in a broad spectrum of human cancer cell lines resulted in potent anti-tumor and anti-metastatic activity both in vitro and in vivo." (PMID 25775124, 2015). "Accordingly, our findings confirm that MDA-7/IL-24 is a relevant therapeutic option even in immune competent mice, both in xenograft models and spontaneous tumor models, and can synergize with the immune system to directly target tumor cells for destruction." (PMID 26474456, 2015). "Compared with the control group, the tumor growth rate and size of IL-24-treated group were significantly reduced and IL-24 combining with 3-MA group were further decreased." (PMID 26361755, 2015).
tumor (continued). "The anti-tumor effects of mda-7/IL-24 are likely mediated not only by autonomous cellular mechanisms through its downstream targets (model), but also through induction of an immune response." (PMID 26460950, 2015). "We investigated the signaling mechanism by which IL-24 phosphorylation regulates its anti-tumor activity." (PMID 26009991, 2015). "To determine the effect of mda-7/IL-24 on tumor development, we next crossed MMTV-rtTA:IL24tet-on mice with MMTV-Her2/neu transgenic mice." (PMID 26460950, 2015). "Little is known about IL-24 protein phosphorylation and its role in IL-24-mediated anti-tumor activities." (PMID 26009991, 2015). "Functional studies showed IL-24 inhibited tumor cell migration and invasion concomitant with reduction in CXCR4 and its downstream targets (pAKTS473, pmTORS2448, pPRAS40T246 and HIF-1α)." (PMID 25775124, 2015). "MDA-7/IL-24 induction also inhibited growth of tumors generated following injection of Her2/Neu tumor cells isolated from triple compound transgenic mice that had not been treated with doxycycline, into the mammary fat pads of isogenic FVB mice." (PMID 26460950, 2015). "IL-24 was known as melanoma differentiation antigen 7 exhibiting proapoptotic activity in a variety of tumor cells and belonging to the IL-10 family of cytokines." (PMID 26517713, 2015). "While our results demonstrated a robust tumor inhibition in triple compound transgenic mice after transgene induction, the expression of mda-7/IL-24 was found to be negligible in tumors harvested prior to euthanasia." (PMID 26460950, 2015). "Our results illustrate that MDA-7/IL-24 delayed tumor onset, suppressed tumor growth and also had anti-tumor “bystander” effects." (PMID 26474456, 2015). "Our third strategy was to co-express both a tumor promoting gene, Erbb2, and MDA-7/IL-24 endogenously in the mammary gland, and to follow tumor progression." (PMID 26474456, 2015). "We further demonstrated that the induction of gas3 by mda-7/IL-24 inhibits attachment and proliferation of tumor cells in vitro and in vivo by blocking interaction of β1 integrin with fibronectin." (PMID 26460950, 2015). "In this model, we used a tumor-specific conditionally replicating virus expressing MDA-7/IL-24 (designated a cancer terminator virus or CTV)." (PMID 26474456, 2015). "A potential role for ceramide production (ceramide synthase, PP2A) and generation of reactive oxygen species as a consequence of induction of ER stress by mda-7/IL-24 in tumor cells has also been demonstrated." (PMID 26460950, 2015). "Although IL–24 was reported to be a tumor suppressor, the biological functions of IL–20 and IL–24 are different." (PMID 26440411, 2015). "Previous studies from our laboratory and others have demonstrated that IL-24 has anti-tumor, anti-metastatic, and anti-angiogenic activities." (PMID 26009991, 2015). "After supplement TRF, the expression of IL-24 mRNA, a cytokine reported to have antitumor effects, increased 2-fold in the tumor tissues of BALB/c mice." (PMID 25807493, 2015). "More importantly, the inhibitory activity on tumor cell migration was greatly enhanced when AMD3100 was combined with IL-24." (PMID 25775124, 2015). "The mechanism by which mda-7/IL-24 exerts its tumor suppressor activity has been extensively studied in the past decade [rev." (PMID 26460950, 2015). "mda-7/IL-24 is an unusual member of the IL-10 cytokine family, with ubiquitous tumor cell proapoptotic activity." (PMID 26361755, 2015). "IL24 mRNA and protein levels are low in cell lines derived from these tumors and adenoviral overexpression of IL24 increased tumor cell apoptosis and decreased tumor cell migration and invasion." (PMID 26498364, 2015). "A tumor cell invasion assay also showed that IL-24 significantly reduced the number of cells invading through Matrigel compared to control cells at all-time points tested (P<0.05)." (PMID 25775124, 2015).
tumor (continued). "The upregulation of genes implicated in anti- tumor immune responses was observed, including CCL3 (Chemokine Ligand 3), the Natural Killer cell ligand; ULBP2 and IL24." (PMID 26304929, 2015). "It is clear that induction of mda-7/IL-24 significantly reduced tumor progression (P = 0.005) with hazard ratio of 2.7." (PMID 26460950, 2015). "Treatment of recipient mice with doxycycline to induce mda-7/IL-24 expression significantly inhibited tumor growth compared with untreated mice (P < 0.03)." (PMID 26460950, 2015). "Our data indicate that tumor volume and mass of the IL-24 treated group was significantly less than that of the 3-MA treated group and control group, while the combination of 3-MA and IL-24 group was even less than the IL-24 group." (PMID 26361755, 2015). "To evaluate the relevance of MDA-7/IL-24 in suppression of tumor growth in immune competent mice, we initially utilized the MMTV-PyMT transgenic mouse model." (PMID 26474456, 2015). "In contrast, IL-24 significantly inhibited tumor cell migration both in the absence and presence of SDF-1(P<0.05)." (PMID 25775124, 2015). "Transfection of miR-205 into KB oral cancer cells strongly induced IL-24, a well-known cytokine acting as a tumor suppressor in a range of tumor tissues." (PMID 25590298, 2015). "In this model, we observed a significant delay in tumor onset in the compound transgenic mice expressing both mda-7/IL-24 and Erbb2 transgenes as compared to the MMTV-Erbb2 littermate controls." (PMID 26474456, 2015). "In another study, micro-RNA-205 induced the expression of tumor suppressor genes IL-24 and IL-32 at both the messenger RNA and protein levels." (PMID 25590298, 2015). "Despite this progress, there is only limited direct evidence for tumor suppressor activity by MDA-7/IL-24 in immune-competent transgenic mice." (PMID 26460950, 2015). "Our results indicate that disruption of CXCR4 signaling by IL-24 results in inhibition of both tumor cell migration and invasion." (PMID 25775124, 2015). "IL-24 is the only IL-10 cytokine family member whose functions are regulated by PTMs, analogous to classical tumor suppressors." (PMID 26009991, 2015). "Despite extensive studies, questions still remain about how to further enhance the anti-tumor effect of IL-24." (PMID 26361755, 2015). "After 30 days treatment, the mean tumor weight and mean tumor volumes of the IL-24 combining with 3-MA group were significantly reduced by 36.21 and 52.03 %, compared with the IL-24 group." (PMID 26361755, 2015). "Functional studies showed that only IL-24wt significantly inhibited cell growth and colony formation, induced G2/M cell-cycle arrest, and activated caspase-9, PARP, and JNK, indicating that phosphorylation is required for IL-24 to exert anti-tumor effects." (PMID 26009991, 2015). "Triple compound transgenic mice treated with doxycycline exhibited a strong inhibition of tumor development, demonstrating tumor suppressor activity by MDA-7/IL-24 in immune-competent mice." (PMID 26460950, 2015). "The intermediate-length expression ofAdLTR2EF1α-IL-24 is conducive to exerting the anti-tumor “bystander” effect." (PMID 26361755, 2015). "The findings in that paper provide further proof of the relevance of MDA-7/IL-24 in tumor suppression in mouse models with an intact immune system." (PMID 26460950, 2015). "IL-24, alternatively, has been predominantly studied in tumor immunology and has exhibited great promise as an anti-tumor therapeutic cytokine." (PMID 24699268, 2014). "This showed that IL-24 inhibited the expression of the antiapoptotic protein and increased the expression of the apoptotic protein to promote tumor cell apoptosis." (PMID 24527085, 2014). "IL24 is considered as a tumor suppressor and can selectively induce apoptosis in cancer cells without affecting normal cells." (PMID 24387160, 2014). "In a separate study we showed IL-24 can also modulate angiogenesis by suppressing growth factors produced by tumor cells." (PMID 24377906, 2013).
tumor (continued). "Both of these studies showed loss of IL-24 protein expression correlated with disease progression and concluded IL-24 likely functions as a tumor suppressor." (PMID 24377906, 2013). "Additional investigation of the activation of the type I IL-20 receptor complex by both IL-19 and IL-24 and the subsequent intracellular responses in tumor cells is needed." (PMID 24130695, 2013). "Exogenous expression of IL-24 in tumor cells resulted in ROS production which in turn deregulated mitochondrial function via PERK dependent generation of lipid second messenger ceramide leading to cell death." (PMID 24377906, 2013). "Treatment of lung tumor cells with Ad-IL24 in combination with radiation downregulated DNA-repair enzymes resulting in enhanced radiation-induced DNA damage in tumor cells and tumor regression." (PMID 24377906, 2013). "In another study, intratumoral injection of Ad-IL24 into a flank tumor resulted in shrinkage of contralateral tumor." (PMID 24377906, 2013). "Since the initial report of IL-24 functioning as a tumor suppressor gene, studies from our laboratory and others have tested IL-24 as an anticancer drug for the treatment of a broad-spectrum of human cancers." (PMID 24377906, 2013). "Treatment with SP600125, a JNK inhibitor abrogated the tumor cell killing demonstrating JNK was required for IL-24-mediated tumor cell killing." (PMID 24377906, 2013). "The results from these studies demonstrate IL-24 can efficiently eliminate both tumor cells and CSCs and thus IL-24-based therapy is an attractive therapy option for the treatment of cancer." (PMID 24377906, 2013). "Clinical studies supporting IL-24 is a tumor suppressor or functions as a tumor suppressor was reported by two independent studies." (PMID 24377906, 2013). "With the discovery of cancer stem cells (CSCs) or tumor-initiating cells (TICs) and their role in contributing to tumor relapse and therapy resistance, emphasis has recently shifted towards testing the antitumor activity of IL-24 on CSCs." (PMID 24377906, 2013). "In general, we found that the entire family of IL-10 cytokines including IL-10, IL-19, IL-20, IL-22 and IL-24 was increased in tumor compared to normal skin." (PMID 23667456, 2013). "Although ligand-receptor mediated cell killing was demonstrated, the receptor utilization by IL-24 protein varied among tumor types." (PMID 24377906, 2013). "From a clinical perspective, the advantage of using IL-24 as an anticancer drug is that tumor cells often use multiple signaling pathways to escape from the cytotoxic effects of a drug." (PMID 24377906, 2013). "It will be evident from the detailed description provided in the earlier sections that IL-24 is a potent tumor suppressor/cytokine that modulates several signaling pathways that are required for tumor cell survival, metastasis and angiogenesis." (PMID 24377906, 2013). "The results from this study showed IL-24 inhibited VEGF expression in tumor cells that resulted in diminished signaling to endothelial cell survival thereby causing an antiangiogenic effect." (PMID 24377906, 2013). "This possibility is likely to occur since in a separate study we showed tissue culture supernatant collected from Ad-IL24-infected tumor cells and rich in secreted IL-24 protein when added to HUVEC cells showed reduced activation of Akt." (PMID 24377906, 2013). "Follow-up studies showed that reintroducing exogenous IL-24 gene and restoring protein expression suppressed tumor growth both in vitro and in vivo." (PMID 24377906, 2013). "The last decade has witnessed several laboratories including our own testing IL-24 as anticancer drug against established in vitro and in vivo tumor models." (PMID 24377906, 2013). "Since IL-24 induced ER stress and regulated the UPR/GRP78/BiP pathway, the possibility of IL-24 inducing autophagy-mediated tumor cell death was investigated." (PMID 24377906, 2013).